TLR4 (toll like receptor 4)
Diseases named in the same sentence as TLR4 in open-access papers (continued):
Sharing a sentence is not in itself a finding about the gene and the disease.
tumor (continued). "However, our study found an inverse correlation between PD‐L1 and TLR4 in OSCC, possibly due to their contrasting roles in tumor immunology." (PMID 40762187, 2025). "For example, TLR4 in non-small-cell lung cancer cells can be activated by gram-negative bacteria, which promotes tumor growth and metastasis." (PMID 40463434, 2025). "This stromal retention depended on TLR4 signaling and could be reversed by blocking the CXCL12-CXCR4 axis, restoring T cell migration into the tumor core and enhancing anti-tumor immunity." (PMID 40475782, 2025). "By analysing IL1β, IL10, IL18, TNF-α, TLR4, GATA3, and CD68 expression in 50% of PCa HHV-infected FFPE with an elevated inflammation index (61.8%/21), we detected hyper-expressed levels of IL1β, IL18, and TNF-α in the tumour microenvironment." (PMID 40430084, 2025). "Interaction with host immune cells further accelerates tumor-promoting inflammation: E. coli engages the TLR4/NF-κB signaling axis to induce pro-inflammatory cytokines, including IL-6, IL-8, and TNF-α, which sustain tumor-promoting microenvironments and facilitate angiogenesis." (PMID 41356485, 2025). "Through FadA-E-cadherin binding on Toll-like receptor 4 (TLR4), Fn can accelerate colonic carcinogenesis mainly in the presence of pre-existing genetic alterations, while Fap2-TIGIT binding can promote tumour survival by smouldering anti-tumour immunity." (PMID 40297307, 2025). "This phenomenon, referred to as transmissible ER stress, involves heat-resistant soluble factors, enhanced by lipopolysaccharide (LPS) and sensed via Toll-like receptor 4 (TLR4), suggesting a mechanistic link between inflammation and ER stress within the tumor microenvironment." (PMID 40723802, 2025). "Notably, a sex-dependent response emerged in mice vaccinated with MUC1 C3-liposomes with TLR agonists (TLR4, TLR7/8, and TLR9); male mice exhibited greater tumor suppression than females." (PMID 40284463, 2025). "TLR-4 can significantly reduce the efficacy of 5-FU by promoting the activation of the NLRP3 inflammasome in myeloid-derived suppressor cells (MDSCs) and macrophages within the tumor microenvironment (TME), triggering an inflammatory cascade reaction." (PMID 40404908, 2025). "LPS activates Toll-like receptor 4 (TLR4), leading to NF-κB activation and the subsequent transcription of inflammatory mediators such as IL-6 and TNF-α, thereby fostering chronic low-grade inflammation and tumour progression." (PMID 40647494, 2025). "HMGB1, on the other hand, activates the NF-κB pathway in Mφ via TLR4/RAGE signaling, promoting the secretion of chemokines such as CXCL9/CXCL10 and recruitment of effector T cells into the tumor microenvironment, while inhibiting Mφ polarization towards the M2 phenotype." (PMID 41019083, 2025). "Moreover, stimulation of Toll-like receptor 4 (TLR4) by bacterial lipopolysaccharides induces the expression of proinflammatory genes, contributing to the progression of tumor-promoting inflammation across various cancer types." (PMID 41514613, 2025). "In addition, ATP drives DC maturation and recruits CTLs to the tumor site by binding to the purine receptor P2RX7; and HMGB1 activates Toll-like receptor 4 (TLR4) to enhance pro-inflammatory signaling to accelerate the ICD process." (PMID 40535125, 2025). "This process activates a TLR4-dependent pathway and the CXCL1-CXCR2 axis, leading to the accumulation of polymorphonuclear myeloid-derived suppressor cells (PMN-MDSCs), which facilitate immune evasion and promote tumor progression." (PMID 40004041, 2025). "To us, such spatiotemporal separation ruled out possible local effects on tumor-associated fibroblasts, suggesting that an inability to properly recruit T cells into FRC TLR4-deficient LNs at early stages of an immune response limits vaccine efficacy." (PMID 41216593, 2025).
tumor (continued). "Interestingly, the inhibition of Toll-like receptor 4 (TLR4), achieved through both siRNA and TAK-242 treatment, not only suppressed tumor-promoting signals but also reduced HMGB1 expression, suggesting a self-amplifying HMGB1-TLR4 loop." (PMID 40559922, 2025). "Tumor cells also release adenosine triphosphate (ATP), high mobility group box 1 protein (HMGB1), and calreticulin, which are recognized by cell surface receptors P2X7, CD91, and toll-like receptor 4 (TLR4), respectively, on DCs." (PMID 41375050, 2025). "These pathways may contribute to tumor metastasis by modulating immune and inflammatory responses.TLR4 (Toll-like receptor 4) is a critical member of the Toll-like receptor family and plays a fundamental role in the innate immune system." (PMID 40260255, 2025). "co-encapsulated the STING agonist cyclic diguanylate monophosphate(cdGMP) and TLR4 pathway agonist monophosphoryl lipid A(MPLA) within lipid nanoparticles, which synergized with PD-1 inhibitors to enhance tumor-clearing CD8+ T cell functionality in melanoma-bearing mice." (PMID 40933890, 2025). "As the abundance of the TLR4 and TLR8 in tumor cells did not reflect the mRNA levels detected in PBMC we also speculate that local TLR4 and TLR8 may participate in the regulation of tumor growth in NSCLC patients." (PMID 40025339, 2025). "Our results align with prior studies implicating MAPKs and AKT in MSC resilience and PI3K/AKT, MAPK, AP-1 complex, and NFkB signaling being activated downstream of LPS-induced TLR4 activation, but we extend these findings by linking them to MSC1 cells’ tumor-suppressive behavior." (PMID 40564222, 2025). "It activates Toll-like receptor 4 (TLR4), induces macrophage polarization, and drives the release of proinflammatory cytokines—key processes that contribute to myocardial inflammation, vascular dysfunction, and tumor-promoting immune modulation." (PMID 40564016, 2025). "In CRC, Fn infection can activate the toll-like receptor 4 (TLR4)/myeloid differentiation factor 88 (MyD88)/NF-κB signaling pathway, upregulate IL-17F, IL-21, IL-22 and macrophage inflammatory protein-3 alpha (MIP-3a) to promote tumor cell proliferation." (PMID 41019530, 2025). "Interestingly, the activation of the CXCL10/CXCL11–CXCR3 axis and TLR3/TLR4 signaling pathways suggested that the combination of hyperthermia and radiotherapy could effectively reshape the tumor immune microenvironment and enhance tumor cell sensitivity to cytotoxic attacks." (PMID 41280655, 2025). "A second-generation CAR-M has been developed by integrating intracellular CD3ζ and toll-like receptor 4 intracellular toll/IL-1R (TIR) domains, with the capability to drive M1-like macrophage polarization, exhibiting superior anti-tumor functions relative to first-generation CAR-M." (PMID 39948620, 2025). "However, ACR can upregulate Toll-like receptor 4 (TLR4) expression on the surface of granulocytes, stimulating ROS production via activation of NADPH oxidase (NOX), potentially contributing to tumor regression." (PMID 40285867, 2025). "Key barriers remain: defining tumor-specific TLR4 signaling thresholds (e.g., distinguishing CRC’s pro-metastatic vs. radiotherapy’s anti-tumor effects), optimizing targeted delivery, and addressing confounders like gut dysbiosis (which modulates systemic LPS levels)." (PMID 41181090, 2025). "Importantly, in vivo studies confirmed that combined therapy with the SPHK1 inhibitor PF-543, the TLR4 antagonist TAK-242, and TMZ synergistically suppressed tumor growth and significantly enhanced the efficacy of TMZ." (PMID 41353343, 2025). "In vitro experiments demonstrated that targeted inhibition of TREM1 not only exerted anti-tumor effects but also suppressed the PMT process in GBM and inhibited the activation of the TLR4/PI3K/AKT/mTOR signaling axis, further highlighting its clinical significance in GBM progression." (PMID 41394801, 2025).
tumor (continued). "This review assessed studies on the resistance of several tumor cells to commonly utilized anticancer treatments induced by TLR-4 to better comprehend the phenomena and mechanism of TLR-4-dependent resistance, as well as to put forward suggestions and insights for overcoming tumor resistance." (PMID 40404908, 2025). "For instance, activation of TLR4 can promote the secretion of pro‐inflammatory cytokines and chemokines, such as IL‐6, IL‐10, and TNF‐α, which can create an immunosuppressive microenvironment that facilitates tumour growth and metastasis." (PMID 40696496, 2025). "Mechanistically, TLR4‐initiated signaling converges with STAT3 phosphorylation, facilitating its nuclear translocation, where STAT3 dimerizes with cofactors to transactivate tumor angiogenesis‐related genes." (PMID 40727252, 2025). "Additionally, to further validate TLR4’s role in the therapeutic effects of calcipotriol, we administered RKH to PyMt tumor-bearing mice during calcipotriol treatment." (PMID 39782693, 2025). "While some TLRs, such as TLR2 and TLR4, have shown both promotive and suppressive effects on tumor growth, others like TLR3 and TLR5 offer promising avenues for therapeutic intervention due to their more defined roles in enhancing anti-tumor immunity." (PMID 38903515, 2024). "Additionally, tumor cells activate TAMs through the TLR4/TRIF/NF-κB signaling pathway and upregulate HIF1α-mediated IL-1β production to stimulate EMT of tumor cells." (PMID 38957393, 2024). "It has been found that the M1 phenotype is acquired after being stimulated with pro-inflammatory factors, such as Toll-like receptor 4 (TLR-4) ligands and interferon-gamma (IFN-γ), and then eliminates tumor cells by producing inflammatory factors (e.g., TNF-a)." (PMID 39061427, 2024). "OVA peptides from irradiated or oxaliplatin-treated EG7 tumour cells, but not live tumour cells, were efficiently presented by all but TLR4-/- DCs." (PMID 38353760, 2024). "In addition, a correlation between high TLR4 expression and worse survival rate in OSCC patients has been reported and TLR-2, -4, and -9 seemed to predict invasive tumor growth." (PMID 38593176, 2024). "In order to ensure whether butyrate suppresses BC tumor growth by targeting TLR4-PDXK/SLC25A28 signalling pathway, T47D cells were transfected with the plasmid expressing TLR4 or empty plasmid, and simultaneously treated with 5.0 mM butyrate." (PMID 38833016, 2024). "Moreover, HMGB1 passively released from necrotic cells, binds to toll-like receptor 4 (TLR4) on DCs, facilitates their maturation and the effective presentation of tumor antigens to T cells." (PMID 39209834, 2024). "Gut microbiota-stimulated cathepsin K could mediate Toll-like receptor 4 (TLR4)–dependent M2 Mac polarization and promote tumor metastasis in CRC." (PMID 39280926, 2024). "TLR4 activation induces Akt/IKKα/β/NF-κB activation, upregulating anti-apoptotic protein Bcl-xl, contributing to apoptosis resistance in CRC cells, potentially facilitating tumor immune escape." (PMID 38930793, 2024). "As a result, our previously documented maintenance of tumor development following AdjFluVx treatment could be attributed to TLR4 and TLR9 activation, supporting an immunosuppressed tumor microenvironment." (PMID 38476365, 2024). "In HPV-positive cases, where we could evaluate the normal epithelium surrounding the tumor, we observed a stronger expression of TLR4 in the NILM epithelium (especially in the basal layer) and a downregulation of TLR4 in H-SIL and hr-HPV-integrated SCCs." (PMID 39451550, 2024). "In this study, the expression of FAM110B was positively correlated with various immune checkpoints such as PDCD1, CTLA4, EDNRB, TLR4, etc., indicating that FAM110B may be a new target for tumor immunotherapy." (PMID 39170745, 2024).
tumor (continued). "Studies on the role of TLRs in NSCLCs show that activation of TLR-4 in NSCLC cells leads to increased regulation of pro-inflammatory cytokines and chemokines (TNF-α or CCL2), which contribute to the immunosuppressive nature of the tumor microenvironment." (PMID 39124797, 2024). "When HMGB1 is released from dying cells, the activated TLR4/MyD88 pathway enhances INF-β signal transduction, stimulates immune activity, and up-regulates the expression of PD-L1 in neighboring surviving tumor cells." (PMID 38785969, 2024). "The expression of these cytokines was reduced in tumor-suppressed groups, including PtenΔhep/Tlr4−/− mice and Tlr4−/− BM-transplanted chimeric mice, due to the absence of TLR4 signaling in macrophages." (PMID 37896221, 2023). "Ret and Tlr4 expression were significantly correlated in tumor samples from female but not male ApcMin/+Ret+/− mice." (PMID 39148929, 2023). "A total of 24 hours later, migration of MSCs and OAd-MSC toward tumor cells was confirmed in both WT and TLR4−/− cells, while no basal migration was observed in the absence of stimuli." (PMID 36875156, 2023). "Additionally, patients with a GWR of less than 60% or tumor recurrence had significantly elevated levels of MDSCs and CXCL10/TLR4." (PMID 37345131, 2023). "Furthermore, while treatment with OAd-MSC WT reduced tumor growth by 39%, this reduction was increased to 58% after treatment with OAd-MSC TLR4−/−." (PMID 36875156, 2023). "Moreover, to verify the protein expression of the four genes, including ENTPD1, NLRP3, TLR4, P2RX7, the HPA database was applied for inspection of the expression of the proteins deprived from them in LUAD tumor tissues and normal tissues." (PMID 37553698, 2023). "The present in vitro findings suggest that the GPM-GBM subtype with activated inflammatory TLR4 pathway may respond to MET treatment and that combination treatment with CXCL8/IL8-inhibitor may improve tumor growth control." (PMID 36765551, 2023). "In summary, our study demonstrated that PepO, as a high level of biosafe immunomodulatory molecule, switches TAM from the tumor-promoting M2 to tumor-inhibitory M1 phenotype by interacting with TLR2 and TLR4 and activating PI3K-AKT-mTOR and inhibiting JAK2-STAT3 pathway." (PMID 37925462, 2023). "S. typhimurium strain lacked efficient recognition by TLR4 and failed to colonize tumors sufficiently to suppress tumor growth." (PMID 38090593, 2023). "In vitro experiments showed that culturing BLCA cells with medium culturing M2-type macrophages resulted in activation of the TLR4/STAT3 signaling pathway in BLCA cells, increased expression levels of EMT markers, and enhanced metastatic ability of tumor cells." (PMID 37118734, 2023). "In the high TLR4 expression subgroup, five-year DSS reached 88.9% (95% CI 77.1–100.0) among patients with the highest CD3–CD8 tumor–stroma index, falling to 39.7% (95% CI 26.4–53.0; p < 0.001, log-rank test) among patients with the lowest CD3–CD8 tumor–stroma index." (PMID 36649244, 2023). "This led to the assumption that although ART inhibited expression of CLEC12A, it did not affect the downstream events in a tumor cell via TLR4." (PMID 38144525, 2023). "When looking at all tumor stages, there was no significant impact on OS in low vs high TLR4 expressing tumors." (PMID 35841426, 2023). "This increased tumor infiltration in the OAd-MSC TLR4−/− group was also observed in regard to innate immune populations, as the group treated with OAd-MSC TLR4−/− showed significant higher density of myeloid cells and macrophages than those treated with either PBS or OAd-MSC WT." (PMID 36875156, 2023). "Then we also evaluated the anti-tumor property of PepO in TLR2−/− and TLR4−/− mice." (PMID 37925462, 2023). "Antibiotics totally abrogated inulin-mediated anti-tumor effect, demonstrating that inulin fails to directly activate ɣδ T cells via TLR-4, rather, its effect is microbiota-mediated." (PMID 36875124, 2023).
tumor (continued). "Toll-like receptor 4/9-cyclooxygenase-2 (COX2) signaling and interleukin (IL)-1β/epidermal growth factor receptor (EGFR)/extracellular signal-regulated kinase (ERK) signaling in tumor cells can be activated by NETs." (PMID 37958984, 2023). "Finally, in order to investigate if a PTX3/TLR4 autocrine loop of stimulation exists in TNBC cells, the expression of PTX3 in MDA-MB-231 shNT cells and tumor xenografts was assessed after TLR4 inhibition." (PMID 37749607, 2023). "However, there is limited evidence supporting the link between tumor-derived paracrine ENO1 and TLR4 expression in macrophages." (PMID 36614179, 2023). "Additionally, propolis has been found to inhibit tumor cell proliferation through various signal pathways, including MAPK, PI3K/AKT/mTOR, JAK-STAT, TLR4-NF-κB, VEGF, and TGFβ." (PMID 37892405, 2023). "Previous study indicated that recombinant RPLP2 with Toll-like receptor 4 (TLR4) could induce the maturation and activation of DCs, and pulse tumor-specific antigen, to induce the activation of tumor-specific CD8IFN-γ T cells followed by tumor clearance." (PMID 37980521, 2023). "Also, blocking CXCL10/TLR4/MMP14 signaling to inhibit MDSCs mobilization and tumor cells invasion and metastasis will present a great potential for developing novel treatment strategies against HCC malignant progression and recurrence." (PMID 37007125, 2023). "Recent research found that FSTL1 mainly derived from CAFs in human HCC could promote tumor growth, metastasis, and therapy resistance by activating AKT/mTOR/4EBP1/c-myc pathway via binding to toll-like receptors 4 (TLR4) on HCC cells." (PMID 37007125, 2023). "HMGB1, being a nuclear nonhistone protein and an extracellularly secreted cytokine can interact with EPHB4, NF-κB, TLR4 and MIA, to promote cancer cell proliferation, migration, metastasis, innate immune response, and tumor escape while also affecting autophagy." (PMID 37511951, 2023). "Concomitantly, ART induced apoptosis of tumor cells, irrespective of the status of TLR4, leading us to assume that ART adopted a non-canonical pathway which differentiated the role of CLEC12A in solid tumors from that known in myeloid cells." (PMID 38144525, 2023). "Cell surface TLRs, including TLR1, TLR2, TLR4, TLR5, TLR6, and TLR10, can actively capture extracellular information, including tumor cell-released DAMPs or apoptotic cancer cell fragments, such as HMGB1, HSP, and S100, as well as extracellular vesicles containing changed cell components." (PMID 36911674, 2023). "In summary, TLR4 plays a crucial role in the upregulation and expansion of MDSCs, which contribute to HCC development by impairing the function of DCs and suppressing the activation of tumor-specific T cells." (PMID 37345131, 2023). "HMGB1 can activate TLR2 and TLR4 on dendritic cells (DCs) to initiate antigen presentation and cytokine secretion, activating antigen‐specific CD4+ T cells and CD8+ T cells to recognize and eradicate tumor cells." (PMID 37945630, 2023). "The activation of TLR4 on macrophages increases the production of IL-10 and C-C Motif Chemokine Ligand 22 (CCL22) that promote the expansion and activation of CD4+CD25highFOXP3+ Tregs, suppressing immune responses against the tumor." (PMID 37345131, 2023). "TLR4 function is similar to TLR2 because of the common signaling checkpoint (MyD88) they share, and activating NF-κB pathway, which could lead to tumor cell proliferation, apoptosis inhibition, and metastasis." (PMID 37283745, 2023). "Beside that, it has been reported that TLR4 may act as a cancer stem cells (CSC) marker, prompting tumor invasion and migration, which contributes to the poor prognosis of HCC." (PMID 36647071, 2023). "Moreover, M-MDSCs can suppress tumor immunity via the CXCL10/TLR4/MMP14 signaling, thereby increasing tumor recurrence after liver transplantation." (PMID 36773210, 2023).